NHSL1-AS1 (NHSL1 antisense RNA 1)
Synonyms: FLJ46906
Gene: Long non-coding RNA gene on chromosome 6 (138,691,730 to 138,697,290, forward strand). Ensembl gene ENSG00000225177.
Diseases named in the same sentence as NHSL1-AS1 in open-access papers:
NHSL1-AS1 is named in the same sentence as 1 disease in open-access papers, as found by Europe PMC text mining. Sharing a sentence is not in itself a finding about the gene and the disease.
NHSL1-AS1 shares sentences with these, for which no sentence is quoted: infection (1 paper).